MYO19 (myosin XIX)
Description:
Actin-based motor molecule with ATPase activity that localizes to the mitochondrion outer membrane. Motor protein that moves towards the plus-end of actin filaments (By similarity). Required for mitochondrial inheritance during mitosis. May be involved in mitochondrial transport or positioning.
Synonyms: MYOHD1; FLJ22865
Tractability: Antibody: UniProt places it where antibodies can reach, with high confidence. PROTAC: ubiquitination databases record sites on it; its protein half-life has been measured.
Gene: Protein-coding gene on chromosome 17 (36,495,118 to 36,545,884, reverse strand). Ensembl gene ENSG00000278259.
Subcellular location: Mitochondrion outer membrane; Cytoplasm, cytoskeleton
Subcellular location (Human Protein Atlas): Mitochondria; Cytosol
Pathways (Reactome):
Signal Transduction: RHOT1 GTPase cycle; RHOT2 GTPase cycle
Gene Ontology:
Molecular function: actin binding; ATP hydrolysis activity; actin filament binding; ATP binding; cytoskeletal motor activity; cytoskeletal protein binding; myosin light chain binding; plus-end directed microfilament motor activity
Biological process: mitochondrion migration along actin filament; regulation of cytokinesis; regulation of mitochondrial fission; endocytosis; establishment of mitochondrion localization
Cellular component: cytosol; mitochondrial outer membrane; mitochondrion; actin cytoskeleton; cytoskeleton; myosin complex
Genetic constraint (gnomAD): Loss-of-function variants: 120 observed, 113.02 expected, observed/expected ratio (o/e) 1.06, 90% interval 0.92 to 1.24. The upper end of that interval is the gene's LOEUF score, 1.24, which puts it in group 5 of 6, group 1 being the genes least tolerant of losing a copy. Missense variants: 1,164 observed, 1,169.9 expected, observed/expected ratio (o/e) 0.99, 90% interval 0.95 to 1.04. Synonymous variants: 509 observed, 456.5 expected, observed/expected ratio (o/e) 1.12, 90% interval 1.04 to 1.2.
Homologues: Orthologues: chimpanzee MYO19 (99% identical), macaque MYO19 (95% identical), pig MYO19 (85% identical), dog MYO19 (85% identical), rabbit MYO19 (85% identical), guinea pig MYO19 (82% identical), mouse Myo19 (82% identical), rat Myo19 (81% identical), tropical clawed frog myo19 (57% identical), zebrafish myo19 (35% identical). Paralogues in human: MYO5A (33% identical), MYO5B (32% identical), MYO5C (31% identical), MYO7B (28% identical), MYO7A (27% identical), MYH4 (27% identical), MYH7B (27% identical), MYH2 (26% identical), MYH8 (26% identical), MYO10 (26% identical), MYH1 (26% identical), MYH7 (26% identical), and 32 more.
Diseases named in the same sentence as MYO19 in open-access papers:
MYO19 is named in the same sentence as 20 diseases in open-access papers, as found by Europe PMC text mining. Sharing a sentence is not in itself a finding about the gene and the disease. The quoted sentences say what the papers report.
breast carcinoma (4 papers, 2015 to 2025). "Paired-end RNA-seq studies associated Myo19 fusions with breast cancer." (PMID 41227303, 2025). "Studies have shown that dysregulation of MYO19 is associated with gliomas and breast cancer." (PMID 39091293, 2024). "Genome-wide association studies suggest that Myo19 may involve in ovarian cancer, pancreatic ductal adenocarcinoma and breast cancer but whether it may play a tumor suppressive role is unclear." (PMID 35562374, 2022). "In Myo19 deleted MDA-MB-231 breast cancer cells, we detected decreased maximal OCR and a little increased basal ECAR, showing a tilted metabolic balance." (PMID 35562374, 2022).
glioma (3 papers, 2015 to 2024). A benign or malignant brain and spinal cord tumor that arises from glial cells (astrocytes, oligodendrocytes, ependymal cells). "Adhesion in a human primary glioblastoma cell line was positively correlated with the cellular content of mitochondria and targeted sequencing identified Myo19 as a familial glioma candidate gene." (PMID 34013964, 2021).
chronic kidney disease (1 paper, 2025). Impairment of the renal function secondary to chronic kidney damage persisting for three or more months. "A recent genome-wide association study of clinically diagnosed chronic kidney disease (CDK) identified Myo19 as a likely candidate gene relevant for kidney function." (PMID 41227303, 2025).
female infertility (1 paper, 2025). Diminished or absent ability of a female to achieve conception. "Mutations on chromosome 11 in mice in the area of the Myo19 gene have been associated with prenatal and postnatal lethality and male and female infertility." (PMID 41227303, 2025).
Hypertension (1 paper, 2025). The presence of chronic increased pressure in the systemic arterial system. "Since MYO19 plays a role in mitochondrial dynamics, disruptions in its function could worsen the effects of smoking and hypertension on cellular health, particularly in the cardiovascular system." (PMID 41480028, 2025).
primary brain tumors (1 paper, 2025). "Two missense mutations in the Myo19 gene were identified in persons with familial glioma, a cancer that accounts for most of malignant primary brain tumors." (PMID 41227303, 2025).
renal clear cell carcinoma (1 paper, 2025). "MYO19 is underexpressed in thyroid and renal clear cell carcinoma, and highly expressed in the remaining tumors." (PMID 40839681, 2025).
Splenomegaly (1 paper, 2025). Abnormal increased size of the spleen. "But it remains to be seen which cells contribute to splenomegaly in the Myo19-deficient female mice." (PMID 41227303, 2025). "Therefore, alterations in mitochondrial dynamics in Myo19-deficient mice may explain the observed splenomegaly." (PMID 41227303, 2025).
Waardenburg syndrome (1 paper, 2022). A disorder characterized by varying degrees of deafness and minor defects in structures arising from neural crest, including pigmentation anomalies of eyes, hair, and skin. "Six new genes were associated with NSHI: INPP4B, CCDC141, MYO19, DNAH11, SOX9, and POTEI; and one new gene, PAX8, was associated with Waardenburg syndrome." (PMID 35440622, 2022).
cancer (9 papers, 2007 to 2025). A tumor composed of atypical neoplastic, often pleomorphic cells that invade other tissues. "MYO19, a mitochondria-associated myosin motor protein, has garnered increasing attention in cancer research." (PMID 41568382, 2025). "MYO19, a mitochondrial actin-based motor protein, has been implicated in mitochondrial trafficking and cancer progression." (PMID 41568382, 2025). "Myo19 downregulation is seen in invasive cancers such as diffuse-type gastric carcinoma, hinting at a potential role of Myo19 loss in tumor invasiveness." (PMID 38279020, 2024). "Of the mutated genes identified, three genes, which included a cancer-related gene MYO19, were found to have expressional changes in the same cases by the transcriptome analysis." (PMID 26429873, 2015). "MYO19-deficient can impaired mitochondrial function and enhance ROS generation in cancer cells." (PMID 41568382, 2025). "In addition, mutations in Myo19 have been linked with different cancers." (PMID 41227303, 2025). "Transcriptional profiling of 33 cancer types demonstrated significant MYO19 elevation in 68.2% of malignancies compared to matched normal tissues, with LUSC showing the pronounced differential expression." (PMID 41568382, 2025). "A cross-cancer comparative analysis based on TCGA data revealed significant upregulation of MYO19 in multiple cancer types." (PMID 41568382, 2025). "MYO19 shows widespread positive correlations with immune-related genes across most cancer types, its expression in LUSC exhibits a predominantly negative correlation with these genes." (PMID 41568382, 2025). "This protein was shown to inhibit cancer cell migration, invasion, and EMT by counteracting the role of the associated myosin 19 (MYO19) protein." (PMID 41439026, 2025). "Moreover, we examined the expression levels of MYO19 mRNA and protein across different cancer stages." (PMID 41568382, 2025). "This unique pattern in LUSC suggests that MYO19 may disrupt immune-related pathways or immune gene expression, leading to a distinct tumor immune microenvironment in this cancer type." (PMID 41568382, 2025). "However, whether MYO19 regulates ferroptosis and further cancer progression remains to be clarified." (PMID 41568382, 2025). "The expression levels of DNA2 and MYO19 were significantly upregulated in FDPS at stages 1, 2, 3, and 4 according to individual cancer stage." (PMID 40839681, 2025). "recently reported that MYO19 is upregulated in non-small cell lung cancer (NSCLC) and can enhance cancer cell migration, promoting the expression of EMT markers." (PMID 40236649, 2025). "To investigate the divergent correlations between MYO19 expression and immune-related gene families across various cancer types, we analyzed the correlation matrix of MYO19 expression with chemokines, chemokine receptors, and MHC genes in various cancers." (PMID 41568382, 2025).
tumor (9 papers, 2015 to 2025). "In contrast to its negative associations with immune and inflammatory features, MYO19 expression shows a strong positive correlation with tumor proliferation." (PMID 41568382, 2025). "To further assess the impact of DNA2 and MYO19 on patient prognosis and tumor mutational load, we evaluated stromal, immune and ESTIMAT scores." (PMID 40839681, 2025). "Differently, copy number mutations in MYO19 not only partially inhibited neutrophil infiltration, but also increased tumor infiltration by CD8+ T cells, macrophages and dendritic cells." (PMID 40839681, 2025). "Our findings reveal that MYO19 overexpression is associated with features of tumor progression and ferroptosis resistance in LUSC and is negatively regulated by hsa-miR-520a-3p." (PMID 41568382, 2025). "Myo19 downregulation is seen in many tumors, and Myo19 expression is negatively associated with tumor metastasis in vivo." (PMID 38279020, 2024). "MYO19 expression is positively associated with the tumor proliferation signature (r = 0.452, p < 0.0001), suggesting that MYO19 may promote tumor growth and cellular proliferation." (PMID 41568382, 2025). "MYO19, a mitochondrial trafficking protein, has recently been implicated in oxidative stress and metabolic control, but its role in ferroptosis and tumor immunity remains unclear." (PMID 41568382, 2025). "Thus, whether Myo19 mediated metabolic reprogramming is related to tumor stemness changes and Myo19 associated tumor occurrence awaits future investigation." (PMID 35562374, 2022). "The expression levels of DNA2 and MYO19 were relatively higher in HCC patients with tumor grade 3 compared with tumor grades 1 and 2 (P < 0.05)." (PMID 40839681, 2025). "The regulation of MYO19 by hsa-miR-520a-3p highlights a critical axis influencing tumor progression, immune evasion, and ferroptosis in LUSC." (PMID 41568382, 2025). "To further explore the role of MYO19 in the tumor microenvironment of LUSC, we assessed its correlation with microenvironmental scores." (PMID 41568382, 2025). "Future studies are needed to further uncover how MYO19 regulates ferroptosis in tumor cells through downstream genes." (PMID 41568382, 2025). "It is interesting that our identification of hsa-miR-520a-3p as a tumor-suppressive regulator of MYO19 highlights the role of microRNAs in controlling ferroptosis and immune pathways in LUSC." (PMID 41568382, 2025). "The downregulation of hsa-miR-520a-3p in tumors disrupts its regulatory suppression of MYO19, leading to MYO19 overexpression and potentially contributing to immune evasion, tumor proliferation, and migration." (PMID 41568382, 2025). "The TIDE score, which evaluates tumor immune dysfunction and exclusion, is significantly higher in the MYO19-high group compared to the MYO19-low and normal groups (Kruskal-Wallis test, p < 0.001)." (PMID 41568382, 2025). "The result revealed that MYO19 was significantly upregulated in multiple tumor types and correlated with unfavorable prognosis." (PMID 41568382, 2025). "Our findings indicate that the expression of mitochondrial MYO19 and DNA2 is significantly associated with the tumor infiltration of various immune cells, including B cells, T cells (CD8+ and CD4+), neutrophils, macrophages, and dendritic cells." (PMID 40839681, 2025). "Correspondingly, heavier tumor weight was measured in ed-Myo19 group in comparison with Blank and wt-POLA2 groups." (PMID 40366506, 2025). "Here, we found MYO19, a mitochondrially localized myosin, was significantly overexpressed in LUSC and associated with poor prognosis, advanced tumor stages and reduced immune infiltration, suggesting that MYO19 has a certain diagnostic and prognosis value of LUSC treatment." (PMID 41568382, 2025). "MYO19 expression negatively correlates with the inflammatory response signature (r = -0.479, p < 0.0001), suggesting suppression of inflammatory processes within the tumor microenvironment." (PMID 41568382, 2025).
tumor (continued). "Finally, we observe that the absence of mitochondria cristae remodeling proteins including the mitochondria-localized actin motor Myosin 19 (Myo19) enhances ROS gradient and promotes tumor dissemination." (PMID 38279020, 2024). "Furthermore, MYO19 may coordinate tumor cell migration and epithelial-mesenchymal transition (EMT) via protein-protein interactions, thereby promoting invasive and metastatic phenotypes." (PMID 41568382, 2025). "Our findings indicate that MYO19 promotes the malignant biological progression of HCC and may be closely related to the tumor microenvironment (TME)." (PMID 40839681, 2025).
MYO19 also shares sentences with these, for which no sentence is quoted: glioblastoma (2 papers); cardiovascular disorder (1); colorectal cancer (1); inflammatory bowel disease (1); lung squamous cell carcinoma (1); lymph node metastasis (1); ovarian carcinoma (1); pancreatic ductal adenocarcinoma (1); periodontitis (1).